EPO (erythropoietin)
Diseases named in the same sentence as EPO in open-access papers (continued):
Sharing a sentence is not in itself a finding about the gene and the disease.
anemia (continued). "Anemia of inflammation is multifactorial and involves in part excessive iron sequestration or reduced bioavailability, impaired erythropoietin production and shortened erythrocyte lifespan." (PMID 33123170, 2020). "In tuberculosis patients, anemia is related to the overexpression of pro-inflammatory factors that inhibit erythropoietin and to changes in iron metabolism." (PMID 32472529, 2020). "Recombinant human EPO treatment for managing anemia can therefore be costly, have undesired side effects, and be painful to the patients." (PMID 32290638, 2020). "We therefore injected EPO in mice to produce a model of accelerated erythropoiesis, which occurs during severe anemia to increase production of RBCs." (PMID 32520308, 2020). "Kelleher et al38 explained that anemia correction with erythropoietin (EPO) or RBC transfusion partially reversed hypoxia in small tumors but not in larger ones." (PMID 32954675, 2020). "Since the discovery of HIF, a concept of HIF stabilization has been suggested to support EPO production in CKD anemia." (PMID 32560029, 2020). "Recombinant human erythropoietin and iron therapy were used for alternative effective therapy in anemia." (PMID 33178833, 2020). "Anemia in CKD typically involves an inadequate EPO response to hemoglobin decline, resulting in inappropriately low EPO concentrations for the prevailing hemoglobin levels." (PMID 32823844, 2020). "Examples include recombinant human insulin for the treatment of diabetes, erythropoietin for renal failure‐induced anemia and interferon for viral hepatitis." (PMID 31123862, 2020). "Both anemia and renal dysfunction are commonly present in heart failure, and the use of exogenous EPO has been investigated in such patients." (PMID 33330669, 2020). "They recommend carnitine supplementation for patients undergoing hemodialysis who have erythropoietin-resistant anemia, hypotension during hemodialysis sessions, cardiac dysfunction, and muscle weakness." (PMID 32003308, 2020). "Direct administration of molecules that are induced by HIF-1, such as EPO, are also being evaluated for their ability to protect the heart and kidneys from acute injuries, as well as for treating anemia in CKD." (PMID 33135539, 2020). "In response to anemia, hypoxia induces an increase of EPO production by the kidney, which stimulates erythroblasts to increase ERFE production and thereby suppress hepcidin." (PMID 32899941, 2020). "At the same time, RBV 800 mg/d was introduced (58 kg, haemoglobin (Hb) 14.7 g/dL) but suspended after 2 weeks because of anaemia (Hb 8.0 g/dL) that required 2 units of packed red blood cells at week (W) 4 (Hb 6.8 g/dL) and EPO 10,000 IU weekly." (PMID 32677900, 2020). "In preterm infants born at 27–28 weeks-of-gestation, retrospective analysis of patients treated with EPO for anemia showed that EPO-treated infants had improved neurodevelopmental outcomes." (PMID 32098276, 2020). "First, EPO is a commonly used therapeutic drug with few side effects and is widely used in the clinical treatment of anemia, especially in patients with CKD." (PMID 33292452, 2020). "It is known that patients with ESRD produce insufficient EPO due to kidney dysfunction to satisfy the higher need for EPO resulting in anemia." (PMID 32318578, 2020). "The present study shows that cessation of blood transfusion can be attained in contemporary THA performed with the detection of pre-operative anaemia and the use of an amended EPO regimen given to anaemic patients before the surgery." (PMID 31468111, 2020). "Inadequate production of erythropoietin (EPO) and iron metabolism disorders are considered as the two main causes that contribute to anemia in advanced CKD." (PMID 33178327, 2020). "While the treatment of anemia in CKD involves managing multiple causative factors as highlighted above, the most significant factor is the deficiency of EPO." (PMID 33062481, 2020).
anemia (continued). "In this paper, the effect of JPYS on CKD anemia was studied based on both EPO expression and iron metabolism." (PMID 33178327, 2020). "A reduction in erythropoietin further decreases erythrocyte survival and leads to a chronic inflammatory status that contribute to anemia." (PMID 33331829, 2020). "The increased cytokines (TNF-α, IFN-γ, IL-1 and IL-6) not only directly promote the development of RA, but also inhibit differentiation and proliferation of erythroid progenitor cells, result in the blunt response of erythropoietin to anaemia." (PMID 33198544, 2020). "The administration of exogenous EPO has been suggested to reduce hepcidin levels and therefore to ameliorate anemia of inflammation and iron sequestration." (PMID 31979104, 2020). "Treatment options for anemia include iron (oral and intravenous), erythropoietin stimulating agents (ESAs) and red blood cell transfusion to restore hemoglobin levels." (PMID 31587136, 2020). "In summary, our data indicate that JPYS can correct CKD anemia through induction of EPO production and regulation of iron metabolic targets and the mechanism of which involves in the translational control of HIF-2α protein accumulation via ERK signaling." (PMID 33178327, 2020). "The etiology of anemia in CKD is multifactorial, and the key mechanisms involve relative deficiency of erythropoietin (EPO), iron deficiency and maldistribution, and shortened erythrocyte life span." (PMID 33392212, 2020). "Exogenous recombinant human EPO is widely used for the treatment of anemia and generally has a good safety profile." (PMID 32290638, 2020). "This trend has been previously observed for EPO in anemia in other populations, such as heart failure patients." (PMID 33330669, 2020). "On the other hand, stress erythropoiesis‐driven remodeling of bone microarchitecture, renal erythropoietin‐hypoproduction, and disordered iron homeostasis are involved in anemia‐dependent routes." (PMID 33042736, 2020). "Glycoprotein hormone that influences the production of erythrocytes through erythropoiesis.EPO is used for the treatment of anemia." (PMID 32194578, 2020). "Anemia, which is the consequence of the insufficient production of EPO and a higher demand for EPO, is another critical complication of ESRD and leads to insufficient Hb and RBC production." (PMID 33391009, 2020). "In chronic renal disease, which is common in CanL, anemia also results from decreased erythropoietin production in the kidney." (PMID 32429309, 2020). "Increased erythropoietic activity in response to anemia or exogenous EPO administration enhances ERFE synthesis by erythroblasts." (PMID 33392212, 2020). "EPO also has renoprotective effects, and early treatment of anemia with EPO in CKD patients slows the development in renal dysfunction." (PMID 32154256, 2020). "The National Kidney Foundation recommends carnitine supplementation for 9 months to 1 year for erythropoietin-resistant anemia, hypotension during hemodialysis sessions, cardiac dysfunction, and muscle weakness." (PMID 32003308, 2020). "The second mechanism involved in the pathogenesis of anemia of chronic diseases is impaired production of erythropoietin." (PMID 32560029, 2020). "EPO has been extensively studied in the past years in the context of anemia therapies or erythrocytosis." (PMID 33255601, 2020). "In the present study, we investigated the prognostic role of serum EPO levels in type 2 diabetic patients with anemia." (PMID 31619722, 2019). "Normocytic and normochromic anemia with low erythropoietin levels is present in ~ 25% of patients with hereditary transthyretin amyloidosis." (PMID 31452021, 2019). "Recombinant human erythropoietin (rhEpo) has been widely used in patients suffering from tumor-related or chemotherapy-induced anemia to improve quality of life (QOL) and to increase loco-regional tumor control after RT." (PMID 30700319, 2019).
anemia (continued). "Historically, anabolic-androgenic steroids were utilized for the treatment of anemia instead of erythropoietin in individuals with chronic kidney disease (CKD)." (PMID 31151420, 2019). "It occurs as a response to chronic anemia states as a homeostatic mechanism via the production of erythropoietin." (PMID 31781438, 2019). "Although there are several pathogenic mechanisms for anemia in the CKD patient, Erythropoietin (EPO) deficiency appears as the dominant factor." (PMID 31412807, 2019). "It is important to consider that tissue hypoxia stimulates erythropoietin production, regulating the proliferation and differentiation of hematopoietic progenitor cells in the bone marrow to reverse the anemia." (PMID 31623146, 2019). "Therapeutic EPO products produced by recombinant DNA technology are used to treat anaemia resulting from a variety of medical conditions, and it is also a target of counterfeit medicine and drug abuse." (PMID 30972470, 2019). "P. falciparum causes anemia by reducing red cell counts, while HBV is postulated to increase hemoglobin (Hb) levels by increasing the release of erythropoietin from regenerating hepatic tissues." (PMID 31002731, 2019). "Reticulocytes show a time lag in the response to anemia, with reticulocytes count still being low on Day 0 while erythropoietin is already elevated at presentation." (PMID 31792345, 2019). "Some studies observed normal to increased EPO levels in children with malaria-related anaemia while others showed that there are reduced EPO levels, according to the degree of anaemia." (PMID 30894794, 2019). "There are recently discovered naturally occurring EPO mutations at specific activation sites of EPO, and this is how attenuation or modelling of EPO signalling in hematopoiesis leads to anaemia and other pathologic conditions." (PMID 31727007, 2019). "Forty-five percent of patients required RBV dose reduction, 11% used erythropoietin, and 3 received blood transfusions for management of anemia." (PMID 31389490, 2019). "In response to anemia, ischemic stress or high altitude, EPO production is induced and stimulates erythroid progenitor cells in the bone marrow to expand the erythroid lineage thus markedly increasing erythropoiesis and mature red blood cell production." (PMID 32038269, 2019). "The introduction of recombinant human EPO (rhEPO) and erythropoiesis-stimulating agents (ESAs) has helped limit anemia-related symptoms and reduce the need for repeated blood transfusions." (PMID 31375077, 2019). "In the later stages of CKD, patients have inappropriately low EPO levels for their degree of anemia, which cannot be overcome by extrarenal EPO synthesis." (PMID 29569190, 2019). "In the current study, three-quarters of anemic patients showed inappropriately low EPO levels despite the presence of anemia." (PMID 31619722, 2019). "Recombinant human EPO (rHuEPO) and erythropoiesis-stimulating agents (ESAs) are being applied to correct anemia in patients with CKD." (PMID 30941190, 2019). "From the perspective of anemia improvement, Siwu granules combined with EPO showed the best therapeutic effect." (PMID 31915448, 2019). "The homozygous mutant mice have impaired induction of the canonical HIF-2 target gene erythropoietin and blunted recovery from acute anemia." (PMID 31725783, 2019). "Little is known on the contribution of anemia due to progressive renal dysfunction leading to declining erythropoietin, reduced oxygen carrying capacity and increased polymerization of HbSS in the renal medulla with accentuation of the renal dysfunction." (PMID 31211789, 2019). "The findings have approved EPO for the treatment of anemia associated with CKD and it has been confirmed that EPO elevates and sustains hemoglobin levels to decrease the need for RBC transfusions in ESRD patients." (PMID 31217925, 2019). "Administration of EPO is indicated for patients with anemia and those waiting for surgery and expecting preoperative hematopoietic effects." (PMID 31821342, 2019).
anemia (continued). "We compared the effect of ZnSO4 and recombinant human erythropoietin (rHuEPO) injections on relieving anemia in 5/6-nephrectomized rats." (PMID 31600973, 2019). "Iron deficiency, combined with inadequate erythropoietin production by the kidneys and erythropoietin hyporesponsiveness, results in compromised erythropoiesis, and anemia." (PMID 30614439, 2019). "The use of erythropoiesis-stimulating agents has come under scrutiny after prospective clinical trials using recombinant erythropoietin to correct anemia reported increased incidence of thromboembolic events and cancer-related deaths." (PMID 30700319, 2019). "Anemia usually results in an increased synthesis of EPO in kidneys in minutes to hours, but the response to EPO is blunted in patients with sepsis." (PMID 31183575, 2019). "For example, recombinant erythropoietin (EPO) is routinely used to treat anaemia by stimulating erythrocyte production." (PMID 31326232, 2019). "Ongoing studies indicate that the use of EPO for the treatment of cancer-induced anaemia is related to an increased incidence of cancer progression and reduced survival of patients." (PMID 31316151, 2019). "Herein, targeting HIF stabilization in increasing more physiologic EPO levels offers a novel approach to improve the management of anemia." (PMID 30941190, 2019). "The amount of circulating EPO is normal or elevated in most forms of hereditary anemia, although the amount is often relatively low for the degree of anemia." (PMID 30971944, 2019). "In fact, mice lacking either EPO or EPOR exhibit embryonic lethality due to severe anemia at approximately E13.5 when the liver produces both RBCs and EPO." (PMID 31245372, 2019). "CKD-related oxidative stress occurred by shortening the life of RBCs and EPO activity destruction, which in turn led to normocytic normochromic anemia." (PMID 31915448, 2019). "P. falciparum causes anemia by reducing red cell counts, HBV on the other hand is postulated to increase Hb levels by increasing the release of erythropoietin from regenerating hepatic tissues." (PMID 31002731, 2019). "Treatment of anemia of patients with CKD has significantly changed over 20 years ago with the addition of recombinant human erythropoietin." (PMID 31412807, 2019). "The causes of anemia in patients with chronic kidney disease (CKD) are multi-factorial, including relative or absolute deficiency of erythropoietin (EPO), reduced iron availability related to chronic inflammation, and gastrointestinal blood loss." (PMID 31619187, 2019). "Sickle cell disease (SCD) patients had elevated serum EPO concentrations ranging from the low end of expected for the degree of anemia to lower than expected." (PMID 30971944, 2019). "On the other hand, in cases of cellular hypoxia such as anemia, blood EPO level can reach up to 10000 mU mL−1." (PMID 31139640, 2019). "Erythropoiesis-stimulating agents (ESAs), including EPO, were used routinely to treat anemia in cancer patients receiving myelosuppressive chemotherapy." (PMID 30622244, 2019). "It is also suggested that proinflmammatory cytokines suppress the production or biological activity of erythropoietin in anemia of inflammation." (PMID 31022892, 2019). "The upregulation of EPO-R reported in various solid tumors has raised safety concerns for the use of EPO or ESAs to treat anemia in cancer patients." (PMID 31752873, 2019). "Anemia as well as hypoxia leads to a compensatory increase in serum erythropoietin (EPO) levels to compensate for reduced end organ oxygen delivery." (PMID 30834265, 2019). "The observation of reduced haematocrit as an indicator of anaemia is consistent with previous findings, which was improved following erythropoietin treatment." (PMID 31640237, 2019). "Normal or low concentrations of erythropoietin are found in conditions of primary polycythemia, some erythropoietin-independent anaemias, but also in kidney-derived anaemia." (PMID 31727007, 2019).
anemia (continued). "It is important to consider that all patients should have a careful nutritional and body composition assessment, to implement an exhaustive intervention if required and thus favor an adequate response to the EPO and consequently reduce the presence of anemia." (PMID 31412807, 2019). "This suggests that low EPO levels in the context of anemia/ID are a proxy of tubulointerstitial damage, which is reported to be a predictor of ESKD in type 2 diabetic patients." (PMID 31619722, 2019). "FG-4592 was primarily designed to treat anemia since it can promote erythropoiesis through elevation of erythropoietin." (PMID 30988335, 2019). "Anemia occurs primarily from amphotericin B induced erythropoietin suppression but can also result from hemolysis." (PMID 31330959, 2019). "In combination with the potential destruction of infected reticulocytes, this translates to an inadequately low reticulocyte count at presentation, while erythropoietin is already elevated in response to anemia." (PMID 31792345, 2019). "PHD inhibitors are in clinical trials for anaemia treatment because erythropoietin (EPO) is a HIF target gene." (PMID 30452037, 2019). "Extensive use of recombinant erythropoietin for anemia correction has markedly reduced need for transfusions but still transfusion rate is high." (PMID 30881398, 2019). "Considering the importance of anemia in hemodialysis patients and its complications, in this study, the effect of erythropoietin administration on blood parameters by comparing the methods of subcutaneous and intravenous administrations was investigated." (PMID 30783118, 2019). "The addition of recombinant human erythropoietin (rHuEPO) to the treatment of anemia of renal origin has been the most important advance in this field." (PMID 31412807, 2019). "In the current study, low EPO levels in diabetic patients with anemia predicted rapid eGFR decline, independently of u-LFABP, a tubular biomarker that is known to predict DKD progression." (PMID 31619722, 2019). "EPO and EPOR on the surface of erythroid progenitor cells are required for red blood cell production and mice with targeted deletion of EPO or EPOR die during embryonic development of severe anemia." (PMID 32038269, 2019). "In other words, appropriate EPO production in the context of anemia/ID reflects the endocrinological reservoir of the kidney." (PMID 31619722, 2019). "Recombinant human EPO (rHuEPO) has been used to treat anemia in clinic, and EPO induces cytoprotection via its receptor expressed in tissue against IR injury in different organs such as the lungs, liver, heart, and kidneys." (PMID 31217925, 2019). "Despite the established treatment of anemia and iron deficiency in CKD patients, our result suggests the importance of simultaneous use of EPO-stimulating agents and iron supplements as an effective treatment approach." (PMID 30700016, 2019). "The importance of reduced concentration of erythropoietin is clinically confirmed in early diabetic nephropathy, as it resulted in anaemia which worsened diabetic retinopathy." (PMID 31727007, 2019). "Anemia in CKD is mainly due to inadequate amount of EPO production of injured kidneys, and the EPO deficiency is proposed to be the central feature of CKD associated anemia." (PMID 30941190, 2019). "EPO is a well‐known hematopoietic cytokine that has been widely used to treat patients with anemia (Subiros, Del Barco, & Coro‐Antich, 2012)." (PMID 30920178, 2019). "Most patients had normocytic normochromic anemia which has been described as the characteristic form of anaemia in renal disease due to decreased production of erythropoietin since 1950." (PMID 30961570, 2019). "The pathogenesis of anemia of inflammation contributes to dysregulation of iron homeostasis, impaired proliferation of erythroid progenitor cells, and blunted erythropoietin response." (PMID 31836793, 2019).